MST1 (macrophage stimulating 1)
Diseases named in the same sentence as MST1 in open-access papers (continued):
Sharing a sentence is not in itself a finding about the gene and the disease.
autoimmune disease (12 papers, 2014 to 2024). A disorder resulting from loss of function or tissue destruction of an organ or multiple organs, arising from humoral or cellular immune responses of the individual to their own tissue constituents. "Mst1 deficiency not only leads to anti-infective immune deficiency but also disrupts immune tolerance, resulting in autoimmune diseases." (PMID 37941053, 2023). "Clinical studies have also demonstrated that patients harboring deletion mutations in the kinase MST1 exhibit immunodeficiency syndrome, rendering them susceptible to bacterial, viral, and fungal infections as well as autoimmune diseases." (PMID 37941053, 2023). "Patients with MST1/2 deficiency present susceptibility to the autoimmune diseases and the immunodeficiency syndrome." (PMID 37909712, 2023). "The deficiency of MST1 causes the immunodeficiency syndrome or the autoimmune diseases." (PMID 37909712, 2023). "Moreover, the deficiency of MST1 causes hypergammaglobulinemia with the production of autoantibody, which leads to the autoimmune diseases such as Sjogren’s syndrome and colitis; meanwhile, the hypergammaglobulinemia is associated with increased levels of IgG, IgA, and IgE." (PMID 37909712, 2023). "MST1 maintains normal immune function via regulating immune-related signaling pathways to maintain the immune tolerance and prevent the autoimmune diseases." (PMID 37909712, 2023). "Accordingly, MST1 is an important regulator of Treg cells and is critical for preventing the autoimmune diseases and maintaining the immune homeostasis." (PMID 37909712, 2023). "Decoding the activators and effectors of Mst1 in the immune system will provide cues toward the treatment of some autoimmune disease and immunodeficiency disorders and improve the development of novel drug therapies." (PMID 29459865, 2018). "Together, these in vivo observations underscore the essential role of Mst1 in T cell-mediated adaptive in vivo responses to self Ags in autoimmune diseases." (PMID 24852423, 2014). "The knockout of RAPL or Mst1 also leads to the development of autoimmune diseases." (PMID 32600317, 2020). "Thus, MST1/2 increase the threshold of immune activation and prevent from excessive responses such as autoimmune disease or allergy." (PMID 32435241, 2020). "MST1 and MST1/2 conditional knock-out animals consequently exhibit features of autoimmune disease." (PMID 25097725, 2014). "In mice, in which Mst1/2 were is Treg-specifically mutated, Treg number is not altered at 1 month of age, but decreases significantly with age in peripheral lymphoid tissues, resulting in Th1-associated lethal autoimmune diseases." (PMID 32435241, 2020). "Thus, MST1 signalling in DCs was required for protection against autoimmune diseases of the CNS." (PMID 28145433, 2017). "Recently, increasing evidence suggested that MST1-dependent noncanonical Hippo pathway regulates the functions of immune cells and plays a critical role in various immune-mediated diseases including autoimmune diseases and fibrosis." (PMID 39700261, 2024). "It was recently found that Mst1/2–TAZ signaling inhibits the development of inflammatory Th17 cells and enhances the differentiation of immunosuppressive Treg cells, which is critical for preventing autoimmune disease development and maintaining immune homeostasis." (PMID 38236243, 2024).
dilated cardiomyopathy (12 papers, 2013 to 2026). Cardiomyopathy which is characterized by dilation and contractile dysfunction of the left and right ventricles. "In keeping with this finding, overexpression of Mst1 caused dilated cardiomyopathy due to excessive apoptosis." (PMID 31328787, 2019). "Mst1 plays essential roles in the heart disease since its activation causes cardiomyocyte apoptosis and dilated cardiomyopathy." (PMID 23527007, 2013). "Cardiac-specific over-expression of Mst1 has been shown to cause dilated cardiomyopathy in mice." (PMID 23527007, 2013). "Cardiomyocyte-specific overexpression of MST1 can lead to dilated cardiomyopathy and increase cardiomyocyte apoptosis, while overexpression of dominant negative MST1 (which inhibits endogenous MST1) can significantly reduce I/ R-induced apoptosis." (PMID 40520009, 2025). "Genetic deletion of MST1, SAV1, and LATS results in cardiac hyperplasia, while overexpression of MST1 or LATS2 leads to post-natal dilated cardiomyopathy." (PMID 32778947, 2020). "Methods and Results: We studied the effect of a highly selective antagonist of SDF-1/CXCR4 signaling, AMD3100, on the development of cardiac fibrosis and cardiac function in mice with dilated cardiomyopathy due to cardiac-specific transgenic overexpression of the stress-kinase, Mst1." (PMID 30837882, 2019). "In this study we investigated whether the intake of fibre or direct supplementation with acetate could attenuate the development of HF in a genetic model of dilated cardiomyopathy (DCM) due to overexpression of the cardiac specific mammalian sterile 20-like kinase (Mst1)." (PMID 33087738, 2020). "Supportive to this notion also comes from studies on the cardiomyocyte-restricted genetic interventions that either activate Mst1 (i.e. Mst1-TG) 19, 21 or suppress YAP or TEAD1 (i.e. YAP- or TEAD1-gene deletion) 23, 24, 51, all result in dilated cardiomyopathy with significant interstitial fibrosis." (PMID 36632235, 2023).
Immunodeficiency (12 papers, 2014 to 2023). Failure of the immune system to protect the body adequately from infection, due to the absence or insufficiency of some component process or substance. "Homozygous nonsense mutations of MST1 in humans induce a combined immunodeficiency with severe lymphopenia, neutropenia, and hypergammaglobinemia characterized by recurrent infection." (PMID 32435241, 2020). "The combined phenotypes of immunodeficiency and autoimmunity are recapitulated by mouse models deficient for MST1 alone, or MST1/2 in a T cell–specific manner." (PMID 32435241, 2020). "Specifically, MST1 loss causes combined immunodeficiency with increased susceptibility to bacterial/viral/fungal infections as well as autoimmune signs/symptoms (e.g., hypergammaglobulinemia and autoantibody production)." (PMID 29597279, 2018). "MST1 deficiency has impaired the adaptive immunity of individuals, such as the insufficient vaccination responses, the decrease of T and B lymphocytes, which leads to combined immunodeficiency." (PMID 37909712, 2023). "By analogy with murine Mst1 deficiency and other defects of leucocyte trafficking, this is likely to contribute to immunodeficiency by impairing key aspects of T-cell development and function such as positive selection in the thymus, thymic egress and immune synapse formation in the periphery." (PMID 26801501, 2016). "Their results indicated that Mst1 regarded as a critical regulator of adaptive immune responses, Th1/Th2-dependent cytokine production and as a potential therapeutic target for immune disorders." (PMID 28028462, 2016). "In conclusion, this report implicates Mst1 as a critical regulator of adaptive immune responses, Th1/Th2-dependent cytokine production, and as a potential therapeutic target for immune disorders." (PMID 24852423, 2014). "Notably, embryonic lethality is observed in Mst1 and Mst2 double gene knockout mice, while single gene knockout of Mst1 primarily manifests as immunodeficiency syndrome." (PMID 37941053, 2023). "These insights expand the ever-growing non-canonical functions of MST1 in innate immune cells illustrating the complex role of this kinase in modulating the innate immune system and opens new therapeutic perspectives for those suffering from the MST1 absence-derived immunodeficiency." (PMID 36618429, 2022).
Autoimmunity (10 papers, 2013 to 2024). The occurrence of an immune reaction against the organism's own cells or tissues. "Additional pathological and immunological analyses have revealed that the early death and weight loss in DC-specific MST1-deficient mice were due to a heightened Th17-dependent autoimmunity." (PMID 28145433, 2017). "Mutations in STK4 (MST1) are implicated in a form of autosomal recessive combined immunodeficiency, resulting in recurrent infections (especially Epstein-Barr virus viremia), autoimmunity, and cardiac malformations." (PMID 38361950, 2024). "Our study sheds a new insight into autoimmunity-like phenotypes with T cell immunodeficiency in Mst1-deficient human, and could aid in the development of Treg manipulation and therapeutics." (PMID 24040101, 2013). "One of these genes was MST1, which is found in the high intelligence-pathway and plays a role in autoimmunity." (PMID 37709755, 2023). "High Mst1 and Mst2 (Mst1-Mst2) activity in Tregs is crucial to prevent tumour resistance and autoimmunity." (PMID 32680511, 2020). "Previous studies have demonstrated that MST1 promotes Treg differentiation and prevents autoimmunity and tissue damage." (PMID 31052239, 2019). "In this study, we provide evidence for the essential role of Mst1 in T cell differentiation and autoimmunity, using both genetic and pharmacologic approaches." (PMID 24852423, 2014). "The Mst1 kinase emerges as a critical regulator of lymphocyte function and autoimmunity." (PMID 24852423, 2014). "Furthermore, since GM-CSF-induced DCs are a key player in inflammation and autoimmunity, Mst1 can be a new and considerable therapeutic target in the treatment of GM-CSF-derived inflammatory diseases, such as multiple sclerosis, rheumatoid arthritis, and inflammatory bowel disease." (PMID 31572367, 2019). "Targeting Mst1 and Mst1-mediated signaling pathways that control Th1-dependent cytokine release, IL-2 secretion, and lymphocyte proliferation represents a promising alternative to the current approaches to treat autoimmunity, organ rejection and graft-versus-host disease." (PMID 24852423, 2014). "As MST1 is critical for the proper activities of FOXO, defective MST1–FOXO signaling impairs the differentiation and function of Treg cells, collapsing immune tolerance and thereby provoking autoimmunity." (PMID 31052239, 2019). "In summary, it is shown that a targeting of MST1 in DCs promotes IL-6 along with the expression of IL-6Rα/β and STAT3, thereby contributing to the programming Th17 cell differentiation in the inflammation that arises in both autoimmunity and fungal infection." (PMID 28145433, 2017). "The contribution of Mst1 to Ag-specific immune responses and autoimmunity has not been well defined." (PMID 24852423, 2014). "Mst1 plays a nonredundant role in autoimmunity and is critical for disease induction in a number of autoimmune and inflammatory disease models." (PMID 24852423, 2014). "Our results demonstrated that CD4+ T cell intrinsic defects are responsible for attenuated autoimmunity in Mst1−/− mice and provide further evidence for an essential and non-redundant role of Mst1 expressed in the CD4+ T cell compartment in EAE progression." (PMID 24852423, 2014). "Our analysis of genetic deletion of Mst1 establishes a central and nonredundant role for Mst1 in controlling T cell- and B cell-mediated adaptive immune responses, allorecognition, and autoimmunity." (PMID 24852423, 2014).
heart failure (10 papers, 2013 to 2025). Inability of the heart to pump blood at an adequate rate to meet tissue metabolic requirements. "Mst1 gene deletion activates autophagy and diminishes cardiac remodeling and dysfunction in heart failure." (PMID 33841177, 2021). "Phenotype of mice with constitutive overexpression of Mst1 are consistent with heart failure and DCM13." (PMID 33087738, 2020). "Modulation of Mst1 in Hippo signaling in myocardial I/R injury and heart failure provides salient examples of potential mechanisms by which Pak1 activation may be cardio protective." (PMID 40065530, 2025). "Mst1 is activated in the heart by I/R and during heart failure and promotes apoptosis of CMs25,38." (PMID 39060225, 2024). "Excessive Mst1 activation impairs autophagic flux, leading to the accumulation of dysfunctional mitochondria and increased oxidative stress in cardiomyocytes, thereby contributing to myocardial injury and heart failure." (PMID 39006833, 2024). "However, phosphorylation of BECLIN1 induced by Mst1 impairs autophagy and induces cardiac dysfunction in heart failure." (PMID 33841177, 2021). "Thus, cardiac‐specific Mst1 knockout inhibits ROS‐mediated JNK signalling to block Ang II‐induced cardiomyocyte apoptosis, suggesting Mst1 as a potential therapeutic target for treatment of RAAS‐activated heart failure." (PMID 30338935, 2019).
liver cancer (10 papers, 2011 to 2025). An epithelial or non-epithelial malignant neoplasm that arises from the liver. "In contrast, loss of Hippo kinase activities, as in mice with a genetic deletion of Nf2, Mst1/2, Lats1/2, or Sav1, causes hepatomegaly and liver cancers, including HCC, ICC, and/or the HCC/ICC mixed form." (PMID 33808155, 2021). "Other important issues are to define the clinical correlates of liver cancers that show deficient Mst1/2-Yap regulation, and to determine whether there are druggable targets in this pathway, for example, upstream of Mst1/2 or downstream of Yap1." (PMID 21102585, 2011). "In terms of human liver cancers, it will be important to identify clinically useful biomarkers for deregulation of Mst1/2 signalling in human HCC and CHC." (PMID 21102585, 2011). "Mst1/2, Yap, and Sav1 are now clearly established as regulators of liver cancer pathogenesis, yet many questions remain." (PMID 21102585, 2011). "In particular, it was noted that the depletion of Mst1/2 could cause HCC, which highlighted the significance of the Hippo pathway in restricting the growth of liver cancer." (PMID 37243813, 2023). "The Mst1-JNK pathway is a regulator of mitochondrial homeostasis in metastatic liver cancer cells, and matrine can activate the Mst1-JNK pathway, significantly upregulating JNK phosphorylation and Mst1 expression, leading to mitochondrial fission and apoptosis of liver cancer cells." (PMID 36278230, 2022). "This decrease of MST2 expression may contribute to HCC development as indicated by the observation that MST1/2 knockout mice develop liver cancer, which stress the potential physiological relevance of the current findings." (PMID 33672268, 2021). "Remarkably, acute Mst1/Mst2 deletion caused a doubling in liver mass associated with marked proliferation of hepatocytes, a substantial expansion of oval cell, resistance to FAS-induced apoptosis, and rapid development of liver cancer." (PMID 21102585, 2011). "Moreover, NUMB3/4, with their truncated PTB domains that render them unable to interact with SPTAN1 and activate MST1/2, were preferentially upregulated in liver cancer, along with a reduction of phosphorylated SPTAN1 (p-SPTAN1), which correlated with YAP activation." (PMID 37843276, 2023). "Interestingly, NUMB isoforms 3 and 4, which have a truncated phosphotyrosine-binding (PTB) domain and are thus unable to interact with phosphorylated SPTAN1 and activate MST1/2, were selectively upregulated in liver cancer, which correlated with YAP activation." (PMID 37843276, 2023). "For example, matrine has been shown to activate mitochondrial fission through the Mst1-JNK pathway, leading to mitochondrial dysfunction, oxidative stress and cell apoptosis, thereby exerting anti-liver cancer effects." (PMID 39584140, 2024). "Importantly, NUMB3/4, which do not activate MST1/2, were selectively upregulated in liver cancer cells, possibly acting as an important oncogenic mechanism contributing to malignant proliferation due to defective contact inhibition." (PMID 37843276, 2023).
amyotrophic lateral sclerosis (9 papers, 2013 to 2020). Amyotrophic lateral sclerosis (ALS) is a neurodegenerative disease characterized by progressive muscular paralysis reflecting degeneration of motor neurons in the primary motor cortex, corticospinal tracts, brainstem and spinal cord. "Hippo pathway is also implicated in other neurodegenerative disorders, for example, MST1/2, the mammalian orthologs of Hpo, play a key role in amyotrophic lateral sclerosis (ALS)." (PMID 32232042, 2020). "Mst1 has also been shown to prevent autophagy and facilitates neurodegeneration during amyotrophic lateral sclerosis." (PMID 28446152, 2017). "Moreover, MST1 has been reported to function as a key determinant of neurodegeneration in amyotrophic lateral sclerosis (ALS)." (PMID 32140159, 2020). "Thus, oxidative stress has been shown to regulate motor neuron death through the phosphorylation of FOXO1 by MST1 in amyotrophic lateral sclerosis (ALS) animal models." (PMID 27322327, 2016). "Furthermore, amyotrophic lateral sclerosis (ALS) associated SOD1(G93A) mutant induces dissociation of Mat1 from a redox protein trx-1 and promotes Mst1 activation in spinal cord neurons in a reactive oxygen species-dependent manner." (PMID 23985272, 2013). "Furthermore, MST1 is a key player in amyotrophic lateral sclerosis (ALS)." (PMID 29534050, 2018). "MST1 deletion in an amyotrophic lateral sclerosis (ALS) mouse model delayed disease onset and prolonged survival of mice, thereby linking MST1 to neurodegeneration in ALS." (PMID 25097725, 2014). "Genetically modified mice that model amyotrophic lateral sclerosis (ALS) lose fewer neurons and survive longer if they are knocked out of MST1." (PMID 25183307, 2014).
inflammatory bowel disease (9 papers, 2010 to 2024). A spectrum of small and large bowel inflammatory diseases of unknown etiology. "Genetic instruments for PARK7, GPX1, and MST1 were linked to various digestive system disorders including sclerosing cholangitis and inflammatory bowel disease." (PMID 38887235, 2024). "Three loci (NOD2, MHC, and MST1 3p21) were associated with subphenotypes of inflammatory bowel disease, mainly disease location (essentially fixed over time; median follow-up of 10·5 years)." (PMID 26490195, 2016). "Importantly, this CD versus UC score retained significance even after NOD2, MHC, and MST1 were removed, lending support to the notion that the genetic risk score offers more information about the genetic substructure of inflammatory bowel disease than individual SNP associations alone." (PMID 26490195, 2016).
viral infections (9 papers, 2017 to 2023). "PKR assembles and phosphorylates MST1 by Exo84 exocyst under the viral infection to activate MST1." (PMID 37909712, 2023). "With respect to virus infection, however, we conclude that the increased number of macrophages in spleens of WT mice leads to increased cleavage of pro-MST1 and, thus, to elevated levels of active MST1 during acute infection." (PMID 29222473, 2017).